PRKRA (protein activator of interferon induced protein kinase EIF2AK2)
Diseases named in the same sentence as PRKRA in open-access papers (continued):
Sharing a sentence is not in itself a finding about the gene and the disease.
cancer (6 papers, 2013 to 2023). A tumor composed of atypical neoplastic, often pleomorphic cells that invade other tissues. "One of these three SNPs, rs2740349 (GEMIN4), was associated with altered mRNA expression in carcinoma tissue, and the two other SNPs, rs2059691 (PRKRA) and rs235768 (BMP2), were associated with altered levels of mRNA expression in normal colonic mucosa across genotypes." (PMID 27107574, 2016). "We then compared the expression of PRKRA in PC and normal tissues in the TCGA database, and it was shown that PRKRA was significantly overexpressed in cancer." (PMID 37484321, 2023). "Among these genes, MMP1 was positively correlated with PRKRA expression, and involved in cancer progression and chemoresistance." (PMID 37484321, 2023). "Three SNPs, rs2740349 (GEMIN4) in carcinoma tissue, and rs235768 (BMP2) and rs2059691 (PRKRA) in normal mucosa, were significantly associated with altered mRNA expression levels across genotypes after multiple comparison adjustment." (PMID 27107574, 2016). "The effects of PRKRA on cancer progression and chemoresistance were validated in vitro and in vivo." (PMID 37484321, 2023). "The capacity of PRKRA to influence downstream pathways and miRNA maturation indicates that it may participate in cancer progression." (PMID 37484321, 2023). "We identified and characterized over 3600 somatic mutations in 29 miRNA biogenesis genes and showed that some of the genes are overmutated in specific cancers and/or have recurrent hotspot mutations (e.g. SMAD4 in PAAD, COAD and READ; DICER1 in UCEC; PRKRA in OV and LIN28B in SKCM)." (PMID 33406242, 2021). "However, the role of PRKRA in cancer has rarely been investigated." (PMID 37484321, 2023). "Other interesting examples included AGO4, LIN28A and SMAD2 overmutated in BLCA (an otherwise extremely low-mutation cancer with no mutations in other genes); LIN28B overmutated in SKCM; PRKRA overmutated in OV; and DDX5 overmutated in BRCA and KIRP." (PMID 33406242, 2021). "Based on these observations, we conclude that the growth effects of enoxacin on transformed MEFs are independent of TARBP2 or PRKRA and that enoxacin may act through a mechanism in transformed MEFs that is different to that in cancer cells." (PMID 29467169, 2018). "Moreover, for carcinoma cases, we did not observe any significant association between DROSHA, DGCR8, DICER, TARBP2, or PRKRA mRNA levels and clinical–histopathological parameters such as gender, age, tumor size, or presence of metastasis (data not shown)." (PMID 23671264, 2013).
tumor (5 papers, 2013 to 2023). "PRKRA mRNA/CHROMR gene expression ratio was significantly lower in tumorous tissues than in normal brain samples and was associated with shorter patient survival." (PMID 36950523, 2023). "Both EYA1 and PRKRA are involved in cell proliferation and migration and implicated in tumour suppression and angiogenesis." (PMID 34034517, 2021). "The expression of PRKRA between normal and tumor tissues were compared, and the prognostic value of PRKRA was evaluated." (PMID 37484321, 2023). "When treated with gemcitabine, the tumor growth was inhibited more obviously in the PRKRA knockout group than in the control group and promoted in the PRKRA overexpression group." (PMID 37484321, 2023). "The tumor growth rates significantly decreased after PRKRA knockout and increased after PRKRA overexpression." (PMID 37484321, 2023). "The expression of PRKRA was significantly upregulated in HCC tumor tissues, especially in the HBV-positive group (p < 0.001)." (PMID 35729579, 2022). "In the present study, we found an increase of PRKRA expression in both tumor tissues and peripheral blood samples in HBV-related HCC." (PMID 35729579, 2022). "We further explored the prognostic value of PRKRA and MMP1 in PC and found that PRKRA and MMP1 were overexpressed in tumor tissues and correlated with poor prognosis." (PMID 37484321, 2023). "We then compared the mRNA expression levels of PRKRA in tumor tissues and tumor-adjacent tissues from GSE19665 dataset (n = 5), and these results confirmed the increase expression of PRKRA in HCC (p < 0.001)." (PMID 35729579, 2022). "Similar to the expression pattern of PRKRA, EIF2AK2 was also upregulated both in tumor tissues and peripheral blood samples." (PMID 35729579, 2022). "To explore the possible reasons for increased PRKRA expression and poor prognosis in HBV-related HCC, we compared the mRNA expression of EIF2AK2 in tumor tissues and blood samples from the HBV-related HCC patients." (PMID 35729579, 2022). "Since PRKRA is known to play a role in antiviral response, perhaps our observations of high levels of CHROMR in glioma could play a role in inhibiting PRKRA related antiviral (which is related to anti-tumor) response." (PMID 36950523, 2023).
infection (2 papers, 2020 to 2025). The state of being infected such as from the introduction of a foreign agent such as serum, vaccine, antigenic substance or organism. "The gene encoding PKR is modestly (1.5-2X) upregulated during OM, but the gene of its activator PRKRA is strongly suppressed (to 0.4X) within hours after ME infection." (PMID 32760078, 2020). "These analyses showed that depletion of DOHH, PRKRA, SEL1L, UBE2G2, and ZFP36L2 consistently decreased DENV-2 viral protein and RNA levels during infection of Huh7.5.1 cells (respectively)." (PMID 41372121, 2025).
movement disorder (2 papers, 2023 to 2024). Neurological conditions resulting in abnormal voluntary or involuntary movement, which may impact the speed, fluency, quality and ease of movement. "DYT-PRKRA is a movement disorder caused by mutations in the PRKRA gene, which encodes for PACT, the protein activator of interferon-induced, double-stranded RNA (dsRNA)-activated protein kinase PKR." (PMID 36874028, 2023).
neurodegenerative disease (1 paper, 2023). A disorder of the central nervous system characterized by gradual and progressive loss of neural tissue and neurologic function. "The PRKRA gene plays an important role in the inhibition of translation and induction of apoptosis pathways, and is implicated in neurodegenerative diseases related to inflammation." (PMID 37528149, 2023).
PRKRA also shares sentences with these, for which no sentence is quoted: hepatocellular carcinoma (3 papers); alcohol dependence (1); Cerebral atrophy (1); cervical dystonia (1); colon adenocarcinoma (1); generalized dystonia (1); Hepatic fibrosis (1); inherited dystonia (1); oromandibular dystonia (1); retinal degeneration (1); schizophrenia (1).